FLT3 (fms related receptor tyrosine kinase 3)
Diseases named in the same sentence as FLT3 in open-access papers (continued):
Sharing a sentence is not in itself a finding about the gene and the disease.
tumor (continued). "This fundamental potent antineoplastic activity of compound 21 was attributed to the circumvention of c-Kit, PDGFRẞ, and FLT3 tyrosine kinases and their down proceeding signaling cascades in tumor cells." (PMID 37438819, 2023). "By analyzing samples after therapies (e.g. FLT3 inhibitor-containing or IDH2 inhibitor-containing) it is possible to evaluate changes in the tumor cell population." (PMID 37803464, 2023). "From this perspective, the most recent CAR-T trials have investigated different, more specific targets, such as FLT3, and the preliminary results have shown comparable levels of anti-leukemic activity and lower off-tumor toxicity." (PMID 37762763, 2023). "We utilized a staining/gating scheme that included Flt3 and SIRPα to establish that the 344SQ tumor infiltrating Ly6C+ monocytes are heterogenous." (PMID 37449205, 2023). "Administration of imatinib alone exerted negligible effect on the tumor growth and volume derived from FLT3-IR cells." (PMID 37932786, 2023). "PXD selectively inhibits CSF-1R, c-KIT proto-oncogene receptor tyrosine kinase (KIT), and Fms-like tyrosine kinase 3 internal tandem duplication mutation sinFms-like tyrosine kinase-3 (FLT3-ITD), thus acting as an inhibitor of tumor cell proliferation." (PMID 38075389, 2023). "Treatment with gilteritinib in MV4-11 CDX mice significantly reduced FLT3 activity and resulted in tumor regression." (PMID 36982453, 2023). "In seven pairs of specimens from individuals with LIHC, qRT-PCR and IHC analysis revealed high SPP1 expression in tumor tissue, while FLT3, SOCS2 displayed the reverse trend." (PMID 37346073, 2023). "The ITD of the JM domain of FLT3 (FLT3-ITD) is the most frequent and significant driver of mutation for human AML patients; it demonstrates a high tumor burden and confers an unfavorable prognosis." (PMID 36072760, 2022). "Our results illustrated that increased expression of FLT3 can propel distinct clusters of anti-tumor cells infiltrating in BC." (PMID 36159964, 2022). "As a result of CNV analysis in pan-cancer targeting of these necroptosis risk model genes, FLT3, CD40, and FASLG genes have high CNVs in various tumor types." (PMID 36675706, 2022). "CT053PTSA is a potent inhibitor of MET, AXL, VEGFR-2, FMS-like tyrosine kinase 3 (FLT3) and MERTK, all of which have been implicated in tumor pathogenesis." (PMID 36341335, 2022). "Between 20 and 30% of patients with AML have FLT3-internal tandem duplication (ITD) mutations, and such patients have a high tumor recurrence rate and poor prognosis." (PMID 35684449, 2022). "We found that mice vaccinated with VRP-FLT3 developed a significantly higher level of IgG that reacted to tumor membrane proteins other than FLT3 compared to the PBS control mice." (PMID 35686131, 2022). "Knocking down inducible HSP70 was enough to destabilized FLT3‐ITD protein and inhibit cell proliferation and tumor growth in FLT3‐ITD‐positive AML cells." (PMID 35928554, 2022). "The correlation between FLT3 expression and tumor immune infiltration was jointly analyzed with estimate, ssGSEA, TIMER, and TISIDB." (PMID 36159964, 2022). "We explored the correlation between FLT3 and tumor-infiltrating immune cells (TILs) along with immunoregulatory factors via TIMER, TISIDB database and ssGSEA." (PMID 36159964, 2022). "Another kinase inhibitor, Sorafenib (SOR), acts by inhibiting several different kinases (RAF-1, VEGF, c-KIT, PDGFR, ERK, and FLT3) involved in tumor cell proliferation and angiogenesis." (PMID 35053339, 2022). "AML patients with higher risk scores were predicted to exert a worse sensitivity against anti-tumor agents including Midostaurin (an FLT3 inhibitor), ABT-263 (a BCL-2 inhibitor), Bleomycin, Bosutinib, and Lenalidomide." (PMID 34784264, 2022). "We accessed clinical information to find that elevated expression of FLT3 correlated with early tumor stage and increased survival." (PMID 36159964, 2022).
tumor (continued). "To investigate the production of antibody specific to FLT3 in tumor-bearing mice, we then employed a direct-binding ELISA using a recombinant mouse FLT3 (rFLT3) protein." (PMID 35686131, 2022). "The overexpression of fms-like tyrosine kinase 3 (Flt3) ligand in tumor-bearing mice results in increased numbers of MDSCs that inhibit the antitumor activity of effector immune cells." (PMID 36362050, 2022). "We found that low DNA methylation occurred in AML, induced upregulation of FLT3, that’s a reason for eliciting pro-tumor signaling pathway activation." (PMID 36081495, 2022). "Admittedly, FLT3LG has been shown to bind to FLT3 (receptor) on DCs to stimulate their differentiation and expansion, facilitating tumor antigen cross-presentation and anticancer immune responses." (PMID 36081495, 2022). "This tumour-killing capacity can be synergistically improved by the specific FLT3 inhibitor gilteritinib via upregulation of FLT3 and NKG2DL expression in AML cells." (PMID 35246156, 2022). "Other effects such as cytokine release, CAR T-cell proliferation and persistence, microenvironment modulation, and tumor resistance are all important parameters in the assessment of the possible effectiveness of anti-FLT3 CAR T-cells." (PMID 36289703, 2022). "Sorafenib inhibits several tyrosine kinases, including VEGFR, platelet-derived growth factor receptor (PDGFR), c-Kit, and Flt3, suppressing tumor cell proliferation, inducing apoptosis, and mitigating tumor angiogenesis." (PMID 35205692, 2022). "With the exception of FLT3-ITD, a moderate to significant correlation in the mutational tumor load between cfDNA and PBMCs in the analyzed mutations was observed." (PMID 35884368, 2022). "We found that B cell responses against self-antigen FLT3 and other surface antigens expressed on tumor cells were induced in mice with established disease." (PMID 35686131, 2022). "In the current study, we characterized the role for YAP1, a new tumor suppressor, in the resistance to chemo- and targeted therapy of FLT3-ITD+ AML cells through DNA damage repair." (PMID 35656547, 2022). "In preclinical studies, orally available FLT3/CDK4 dual kinase inhibitor AMG-925 showed efficacy in AML tumor models and inhibited signaling in sorafenib-resistant AML cell lines." (PMID 33401428, 2021). "In a preclinical study, a second-generation FLT3-4-1BB-CD3-CAR T cell was engineered by using the anti-human FLT3 antibody-derived ScFv to targeting the FLT3+ tumor cells." (PMID 34412685, 2021). "Next, the inhibitory efficacy of LT-171-861 against FLT3 was confirmed in cell proliferation screening of tumor cell lines." (PMID 33391463, 2021). "Pexidartinib (Turalio®) has shown efficacy against FLT3-ITD carrying the F691L resistance mutation, but other secondary mutations make the tumour resistant to pexidartinib as well." (PMID 33832508, 2021). "In particular, Sorafenib interacts with BRAF, BRAFV600E, cKIT, and FLT3 on tumor cells and VEGFR2–3 and PDGFRβ on tumor endothelial cells." (PMID 34205656, 2021). "CCT241736 has significant in vivo efficacy against FLT3-ITD human tumor xenograft models and against FLT3-ITD cells with high in vitro relative resistance to the FLT3 inhibitors quizartinib and sorafenib." (PMID 33401428, 2021). "In order to elucidate the role of the signature genes’ biological functions, the association of STMN1, RAP1A, FLT3, HSPA8, ANGPT2, and PGF was positively associated with tumor purity in HCC." (PMID 34178637, 2021). "Next-generation sequencing demonstrated mutations in FLT3, NOTCH2, and KMT2A, microsatellite stability, and a tumor mutational burden of 2 mut/Mb." (PMID 34292677, 2021). "In a glioma mouse model, a tyrosine kinase inhibitor PLX3397 that targets CSF-1R, c-Kit and Flt3 blocks tumor progression through depolarizing M2 phenotype of TAMs and impairing their pro-tumor function." (PMID 34359674, 2021).
tumor (continued). "The combination of VEN with FLT3-tyrosine kinase inhibitor (TKI) induced more durable tumor regression in FLT3-mutant AML cell lines." (PMID 35008186, 2021). "Certain kinases, notably PI3K/Akt, Src, c-MET, VEGFR1/2/3, and FLT3 were over-represented by multiple inhibitors, implying that these targets are likely to be true positives and key mediators of tumor hypoxic adaptation." (PMID 33859738, 2021). "Sorafenib, firstly known for its antiangiogenic effect and approved for treating HCC, RCC and DTC, is found potent in inhibiting FLT3, with a significant anti-tumor effect in the FLT3-ITD mutant AML." (PMID 34820336, 2021). "LT-171-861 displayed higher inhibitory efficacy on FLT3-mutant cell lines than that on other tumor cell lines." (PMID 33391463, 2021). "Lastly, phosphorylation of other RTKs targeted by toceranib including KIT (33%) and Flt-3 (22%) was observed in a relatively small percentage of tumor samples." (PMID 34600548, 2021). "They particularly focused on FLT3 genotypes in malignant cell clusters; FLT3-ITD subclones were contained within primitive cells whereas FLT3-TKD subclones in the same tumor primarily contained differentiated cells." (PMID 34926276, 2021). "Taken together, these results suggested that the combination of Gilteritinib plus ATO was efficacious to reduce the tumor volume in mouse xenograft models of FLT3-ITD mutant AML." (PMID 32565734, 2020). "Recent studies suggest that circulating MYBL2, encoded by the cell-cycle checkpoint gene MYBL2, is detected in AML patients with FLT3-ITD mutations and is closely related to mutant FLT3 expression as well as to tumor cell activity." (PMID 32722298, 2020). "The inactivation of ATM or its downstream effector G6PD also induced synthetic lethality along with FLT3 inhibition by enhancing mitochondrial oxidative stress, which eventually resulted in tumor apoptosis." (PMID 32722298, 2020). "Combination of Gilteritinib with ATO showed synergistic effects on inhibiting proliferation, increasing apoptosis and attenuating invasive ability in FLT3-ITD-mutated cells and reducing tumor growth in nude mice." (PMID 32565734, 2020). "In conclusion, we have demonstrated the high affinity and selectivity that quizartinib and its active metabolite AC886 have for FLT3 and that quizartinib maintains preclinical antitumor activity against midostaurin-resistant tumor models." (PMID 32215183, 2020). "This inhibitor has specificity against CSF1R but also the related receptor FLT3 and has been shown to reduce macrophage numbers and limit tumour growth in several models of transplanted tumours as well as in a FLT3-dependent subset of AML." (PMID 32581720, 2020). "Several patients experienced clinical benefit with tumor mutations in cKIT, CSF-1R, PDGFRα, PDGFRβ, VEGFR1, VEGFR2, FLT3, FGFR2, RET, and TrkA." (PMID 32292573, 2020). "Combing the pervious study and our outcome, the value of the FLT3 in predicting the relapse and survival of tumor patients have been explored." (PMID 33102231, 2020). "This review summarizes the current knowledge about the regulation of FLT3 activity at cellular level and discusses therapeutical options to affect the tumor cells and the microenvironment to impair the haematological aberrations." (PMID 33003568, 2020). "The PDGFR/FLT3 inhibitor crenolanib targets angiogenesis and inhibits tumour growth in vivo unrelated to PDGFR expression." (PMID 31235865, 2019). "Other variants detected in this tumor, such as those inFGFR3,PDGFRA,KDR (c.1416A>T),CSF1R,EGFR,RET,HRAS,PIK3CA,FLT3 (c.1310-3T>C), andSMAD4, are benign." (PMID 32612806, 2019). "Using a mouse xenograft model, we demonstrated that cabozantinib effectively inhibits the FLT3-ITD pathway along with MV4-11-R-derived tumor growth." (PMID 30862120, 2019).
tumor (continued). "Of note, “on-target off-tumor” toxicity against healthy FLT3+ cells were indeed observed with FLT3xCD3 bispecific antibodies that stimulate T cells, as well as with CAR-T cells; for both, such low target antigen levels are sufficient to induce activation." (PMID 31817795, 2019). "This same tumor also had six variants of uncertain significance: ARID2 c.1672C > T p.(R558C), FLT3 c.2546G > A p.(R849H), IGF1R c.3897C > G p.(N1298K), MSH6 c.1157C > G p.(P386R), PBRM1 c.2504G > A p.(R850H), and RNF43 c.1114C > T p.(P372S)." (PMID 31046843, 2019). "Our results demonstrate that gilteritinib potently inhibits tumor growth even in the presence of FL due to comparable inhibitory efficacy against FLT3wt and FLT3-ITD." (PMID 31692922, 2019). "Upregulation of the FLT3 ligand following chemotherapy is another mechanism that contributes to both chemotherapy and FLT3 inhibitor resistance in AML, especially in tumor cells that co-express FLT3-ITD and FLT3 wild-type alleles." (PMID 31069015, 2019). "TG02 exhibited potent antiproliferative effects against various tumor cell lines, induced cell-cycle arrest and apoptosis in murine mutant FLT3 leukemia cells, and induced tumor regression and prolonged survival in murine AML models." (PMID 29471852, 2018). "We found that the Myc network of oncogenes and tumor suppressors is changed in Flt3-ITD myeloproliferative mice compared with wild-type mice." (PMID 30420889, 2018). "Tumor burden in an FLT3 TKI-resistant transplant mouse model was significantly reduced by oral administration of TTT-3002." (PMID 30514344, 2018). "In Mo-DCs and FLT3L-DC-immunized mice however, tumor rejection occurred over 17–40 days (FLT3-DC), or 17–20 days (Mo-DCs)." (PMID 30030558, 2018). "Sunitinib (SU11248), the first FLT3 inhibitor studied in the clinic, plays a role in inhibiting both tumor angiogenesis and tumor cell proliferation, and usually is used with cytarabine against AML cell lines with FL3-ITD mutation." (PMID 29456860, 2018). "Previous reports showed that Hsp90 is overexpressed in tumor cells and protects oncogenic mutant proteins including FLT3/ITD from ubiquitination and degradation." (PMID 30250637, 2018). "Even more profound responses were found in MOLM-16 (FLT3-WT) tumor-bearing SCID/beige mice: ~100% TGI was reached at doses 50 mg/kg in QD schedule and 25 mg/kg in BID schedule." (PMID 29682194, 2018). "The decreased FLT3 activity and high intratumor distribution of gilteritinib translated to tumor regression and improved survival in xenograft and intra-bone marrow transplantation models of FLT3-driven AML." (PMID 28516360, 2017). "Overall, gilteritinib showed consistently potent inhibition of FLT3 in preclinical studies and demonstrated strong efficacy in FLT3-mutant tumor models." (PMID 28516360, 2017). "Phosphorylated FLT3 decreased by approximately 40% compared with control phosphorylation levels in tumor samples within 1 h after single oral administration of 1–10 mg/kg gilteritinib, indicating target inhibition by gilteritinib." (PMID 28516360, 2017). "The effect on tumor burden of inhibiting FLT3 phosphorylation was assessed following 28 days of once-daily oral administration of gilteritinib." (PMID 28516360, 2017). "For tumor cells, the long survival time means the more chances for the activation of additional signaling pathways beside the FLT3." (PMID 29262547, 2017). "We investigated the patients with solid cancers harboring Fms-like tyrosine kinase 3 (FLT3) amplification using targeted sequencing of tumor tissue specimen and FISH assay." (PMID 27906677, 2017). "In order to investigate the sensitivity of patient derived tumor cells on regorafenib and sorafenib, we generated malignant tumor cells from FLT3 amplified tissues as described in Methods." (PMID 27906677, 2017).
tumor (continued). "The protective mechanism appears to include at least in part stromal cell secreted cytokines that activate some of the very same pro-tumor pathways (i.e. phospho-STAT5) activated by oncogenic FLT3." (PMID 28978059, 2017). "SGI‐1776, as a first-generation inhibitor, has high anti-tumour activity in vivo and in vitro by inhibiting FLT3, cyclin D1, MCL, Myc and Pgp." (PMID 27596051, 2016). "Treatment with BGB324 resulted in tumor regression in mice with subcutaneous xenografts of the human FLT3-ITD AML cell line MV4-11." (PMID 27834816, 2016). "Provided the relatively low incidence of the single gene mutations, clonal mutations (detected in >20% of tumor population) were grouped into the JAK/STAT (IL7R, JAK2, JAK1, CRLF2 mutations and CRLF2-rearrangements) and RAS/RTK (FLT3, KRAS, NRAS) pathways." (PMID 26883104, 2016). "We detected an extraordinary level of tumor heterogeneity, with microclonal (mutant allele fraction <0.10) KRAS, NRAS, FLT3, and/or PTPN11 hotspot mutations evident in 31/57 (54.4%) patients." (PMID 27683039, 2016). "In this study, we show that GADS interacts with FLT3 and enhances FLT3 downstream signaling, resulting in aberrant cell proliferation, colony and tumor formation." (PMID 26895103, 2016). "We showed that SLAP2 expression controlled FLT3-ITD mediated cell proliferation, colony formation and tumor formation through suppression of FLT3 downstream signaling by destabilizing the receptor." (PMID 27458164, 2016). "The observation that BEX1 expression promotes apoptosis and inhibits cell proliferation, colony formation and tumor formation induced by FLT3-ITD suggests that BEX1 expression is favorable for AML patients who are positive for the FLT3-ITD mutation." (PMID 26046670, 2015). "FLT3 inhibitor - gold nanoparticle conjugates were fabricated to serve as vehicles for the delivery of anti-tumor drugs." (PMID 26625890, 2015). "CCT241736 significantly inhibited the growth of MV4-11 human FLT3-ITD positive AML tumor xenografts in vivo, with biomarker modulation and free drug exposure consistent with dual FLT3 and Aurora kinase target inhibition." (PMID 26734566, 2015). "In vitro cytotoxicity studies on two cell lines (OCI-AML3 and THP1) demonstrate that FLT3-loaded GNP are promising candidates as vehicles for anti-tumor drugs and show superior therapeutic effect than the freely administered drugs." (PMID 26625890, 2015). "Taken together, our study suggests that BEX1 has a tumor suppressor role in AML and that loss of BEX1 expression results in poor overall survival in FLT3-ITD positive AML patients." (PMID 26046670, 2015). "In vitro cytotoxicity assessment shows that FLT3-incorporated gold nanoparticles are promising candidates as vehicles for anti-tumor drugs and demonstrate superior therapeutic effect comparatively with the bare drugs." (PMID 26625890, 2015). "More investigations in clinical trials and on the other malignancies are necessary to explore the potential anti-tumor activity of FLT3–TKIs." (PMID 25110867, 2014). "Whole genome sequencing of 12 human samples of APL included one case in which FLT3-ITD and PML-RARα were the only recurrent cancer-associated tier 1 somatic mutations in the tumour genome." (PMID 25056697, 2014). "BPR1J-340 also demonstrated pronounced tumor growth inhibition and regression in FLT3-ITD+ AML murine xenograft models." (PMID 24416160, 2014). "It has shown anti-tumor activity against Ba/F3 cells harboring FLT3/ITD mutant and MOLM-13 cells that are resistant to sorafenib both in vitro and in vivo." (PMID 25110867, 2014). "Once the tumors grew into palpable nodules the tumor on one side was treated with RT and systemic fms-like tyrosine kinase-3 (flt-3) ligand was given concomitantly to recruit DCs from the bone marrow." (PMID 25506582, 2014).